SOX2 (SRY-box transcription factor 2)
Diseases named in the same sentence as SOX2 in open-access papers (continued):
Sharing a sentence is not in itself a finding about the gene and the disease.
tumor (continued). "Indeed, downregulation of PPARD reduced vitamin D receptor (VDR) expression and subsequently mitigated its inhibitory effect on the SOX2 promoter, thus promoting SOX2 expression and resulting in tumor growth and drug resistance of colorectal CSCs." (PMID 41148824, 2025). "By modulating the cell cycle, anti-apoptotic pathways, and cell adhesion mechanisms, SOX2 may enhance the adaptability of tumor cells to their surrounding environment." (PMID 39976818, 2025). "Studies indicate that 3D cultures better mimic the tumor microenvironment (TME) and enhance cancer stem cell maintenance, partly through the upregulation of stemness-associated transcription factors such as SOX-2 and NANOG." (PMID 41502502, 2025). "This discrepancy may stem from the distinct biological features of recurrent versus primary malignancies, suggesting that markers like SOX2 could behave differently depending on a tumor’s evolutionary history." (PMID 40227667, 2025). "Additionally, assessment of the expression levels of SOX2/OCT4 proteins in the tumor indicated that, compared with the shRNA-NC group, the expression level of SOX2/OCT4 proteins in the tumor of the shRNA-HIF-1α group decreased." (PMID 39781344, 2025). "Moreover, NCT-503 treatment led to a decrease in the number of tumor cells expressing the stem cell markers SOX2 and Olig2, an increase in the expression of markers associated with DNA repair, and an increase in tumor cell apoptosis." (PMID 40102981, 2025). "The association between SOX2 expression and cortical bone perforation likely reflects not only stemness but also involvement in tumor-driven bone homeostasis." (PMID 41176605, 2025). "In vivo experiments demonstrate that suppressing HIF-1α protein expression reduces the growth rate of subcutaneously formed tumors and decreases the expression levels of proteins associated with the P-PI3K/P-AKT, SOX2/OCT4, and MMP2/MMP9 pathways within the tumor." (PMID 39781344, 2025). "A potential upstream role of SOX2 in regulating cell proliferation and tumor progression was proposed, suggesting that this gene could overcome chemotherapy resistance." (PMID 41463503, 2025). "Consistently, the expression of multiciliation regulators Gmnc, TAp73, and Foxj1, as well as CP epithelial markers Ttr and Aqp1, were significantly reduced in tumor cells irrespective of Sox2 loss." (PMID 40128799, 2025). "In addition, CYP3A5 KO led to a significant reduction in the number of SOX2 + and Ki67 + tumor cells within GBM xenografts." (PMID 39754188, 2025). "Matsika et al54 also showed that among various prognostic parameters (such as lymphovascular invasion, extraprostatic extension, Gleason score, pathological lymph node staging, and pathological tumor staging), SOX2 was only significantly correlated with lymphovascular invasion." (PMID 40821114, 2025). "Interestingly, Metz et al80 found that elevated SOX2 induced a reversible growth arrest state, both in vivo and in vitro, conferring resistance to conventional chemotherapy in tumor cells." (PMID 40821114, 2025). "NANOG, SOX2, and OCT4 were found to be highly expressed in gastric cancer tumor tissues compared with those in adjacent healthy tissues, and their overexpression was associated with tumor size, tumor grade, and overall survival time." (PMID 40806148, 2025). "In addition, we found that the average IHC score of SOX2 was significantly higher in OS tumor tissues versus paracancerous (PARA) tissues." (PMID 39994220, 2025). "Overexpression of SOX2 is associated with the acquisition of stem cell-like characteristics by tumour cells, which may promote tumour initiation, invasion, and metastasis; hence, overexpression of the SOX2 gene or protein can be observed in cancers." (PMID 40723918, 2025). "Furthermore, SOX2's role in maintaining CSCs suggests that it is a key factor in the late stages of metastasis, ensuring the survival and growth of metastatic tumor cells." (PMID 40821114, 2025).
tumor (continued). "SOX2 is known to play a role in cisplatin resistance in other tumor types." (PMID 40643470, 2025). "Notably, we found NES+ and SOX2+ tumor cells in closer proximity to PDGFRβ+ regions, in comparison to MAP2+ cells." (PMID 40562749, 2025). "Corresponding autopsy analysis revealed prominent perivascular infiltration by SOX2-positive tumor cells, suggesting that perivascular tumor cells infiltration may have contributed to reduced DTI-ALPS index." (PMID 41510293, 2025). "At protein level, the expression of LMX1A, LMX1B, and SOX2 was markedly elevated in tumor cells." (PMID 40128799, 2025). "Additionally, SOX2-driven upregulation of CXCL5 in NSCLC promotes the accumulation of tumor-associated neutrophils (TANs), accelerating tumor progression." (PMID 40303413, 2025). "Furthermore, activation not only inhibits the expression of key transcription factors involved in differentiation but also induces the transformation of tumor cells into a cancer stem cell phenotype by upregulating stem cell marker genes like SOX2 and OCT4." (PMID 40621472, 2025). "Moreover, the reduction of HAS3, ABCC5, and SOX2 gene expression induced by Pa + 4Mu, previously observed in vitro, was confirmed in tumor tissue from treated mice." (PMID 39039104, 2024). "SOX2 staining was observed in both the tumor core and the invasive front." (PMID 38275880, 2024). "Taken together, these results suggest that tumor cells under irradiation downregulate their SOX2 expression while upregulating their SOX9 expression, and this inverse regulatory tendency may phenotypically increase their resistance to radiation." (PMID 38275880, 2024). "Indeed, in a 3D Matrigel assay SOX2-silencing in a cancer cell line with concomitant SOX9 expression present a higher tumor-initiating capacity compared with control cells." (PMID 38275880, 2024). "Interestingly, SOX2 immunofluorescence was detected in all (21/21) tumours, whereas SOX2 immunopositivity was detected in 17/55 tumours in the present study." (PMID 38483762, 2024). "In addition, Sox2 expression was observed in primary tumor cells, while Nestin was expressed in recurrent tumors." (PMID 38256907, 2024). "Its high levels in the tumor-free area may be related to SOX2 playing an important role in lung epithelium." (PMID 39272828, 2024). "However, we found that Sox2 representation is increased in aptamer-resistant tumor cells, indicating the survival of a certain group of tumor stem cells." (PMID 38256907, 2024). "However, several reports have claimed that SOX2 can function as a tumor suppressor in certain cancers." (PMID 38334608, 2024). "SOX-2 was reported to play a strong role in promoting tumor progression in different cancer types." (PMID 38864530, 2024). "Moreover, 1 nM hIMB1636-LDP-AE downregulated the protein levels of stem cell markers that included OCT4, SOX2, EpCAM, and Nanog in all four Trop2+ tumor cell lines." (PMID 38654141, 2024). "In addition, we were able to show that Sox2 positive cells are organized in clusters in human tumor specimens." (PMID 38306361, 2024). "In addition, primary PDAC had significantly increased SOX2 stromal expression in comparison to the healthy control group and nearby non-tumor pancreatic tissue (P = 0.002 and P = 0.003)." (PMID 38532463, 2024). "Analysis based on the Spearman correlation coefficient indicated a very weak positive correlation between NSDHL and SOX2 expression in patient tumor tissues (n = 998, r = 0.089, P = 0.005), whereas a negative correlation was found between NSDHL and NANOG expression (n = 998, r = -0.038, P = 0.24)." (PMID 39516821, 2024). "Furthermore, based on the experimental evidence, it has been demonstrated that a combination of 5-FU and radiation can effectively inhibit the immunofluorescence of OCT4 and SOX2 CSC markers in tumor organoids, compared to a single treatment modality." (PMID 38429272, 2024).
tumor (continued). "Though the positive correlation between Tau levels and spherical growth might suggest induction of differentiation, we observed Tau expression in SLGCs with high Sox2 levels, detected Tau-positive tumor cells in GBM slices, and observed Tau in all SLGC lines." (PMID 38306361, 2024). "Thus, in vivo, GSI-mediated inhibition of Notch signaling seems to shift the balance of the tumor cells towards more invasive SOX2+ tumors, which are resistant to GSI." (PMID 39478150, 2024). "It has been demonstrated that Sox2 is capable of promoting tumor neovascularization." (PMID 39098905, 2024). "SOX2 was expressed at lower levels in the single-cell tumor clusters than in the bulk RNA-seq data." (PMID 38609519, 2024). "For instance, prior research has shown that silencing SOX-2 promotes larger tumor development, whereas its overexpression correlates with smaller tumors, a finding consistent with our clonogenic assays showing smaller colonies at higher SOX-2 expression levels." (PMID 39766136, 2024). "Furthermore, Notum promoted tumor sphere formation and tumorigenesis through upregulation of Sox2 by activating the PI3K/AKT signaling pathway." (PMID 37749430, 2024). "Tumor growth was dependent on SOX2 levels, since sgSOX2.1 tumors that still expressed some levels of SOX2 protein grew only slightly faster than the controls, while sgSOX2.2 tumors, which have no detectable SOX2 protein expression, grew much faster than controls." (PMID 38951654, 2024). "Besides, in retinoblastoma, VEGF has been found to stimulate Sox2 expression and enhance tumor invasiveness." (PMID 39098905, 2024). "STIM1/SOX2 expression in tumor cells, as well as microenvironment cells, could contribute to PDAC and AAC tumorigenesis." (PMID 38532463, 2024). "Taken together, omics analyzes presented in this study support the hypothesis that the inverse SOX2/SOX9 expression is involved in tumor progression and resistance to treatment." (PMID 38275880, 2024). "This suggests that the antagonistic relationship between Notch signaling and SOX2 in regulating divergent cell states might apply to several tumor entities." (PMID 39478150, 2024). "This discovery not only provides new insights into the molecular mechanisms of CCA but also suggests potential targets for the development of innovative treatment strategies, such as drugs targeting LINC00511, YTHDF2, or SOX2 to disrupt this loop and curb tumor progression." (PMID 39445001, 2024). "Subsequent multiplex immunofluorescence analysis of the tumor sections confirmed that Hsp70 was predominantly expressed in the regions (ii) and (iii) of VTs, colocalizing with the markers of tumor stem cells (i.e., cells expressing stemness markers SOX2, nestin, and Oct4)." (PMID 39015084, 2024). "Indeed, MK2206, which is an Akt inhibitor, reduced SOX2 protein levels and suppressed tumor spheroid formation in ESCC K450 cells." (PMID 38612911, 2024). "Moreover, CSC percentages and tumor‐initiating capabilities were markedly reduced in cells with SOX2 or SMAD3 stable knockdown as measured by limited dilution and tumorigenic assays." (PMID 39206755, 2024). "However, compared to that in tumor cell clusters, overexpression of SOX2 in radial glial/astrocyte-like and oligodendrocyte cell clusters was more notable." (PMID 38609519, 2024). "Importantly, SOX2 has been extensively studied in the context of cancer, playing a pivotal role in tumor cell proliferation, cancer metastasis, and response to therapies." (PMID 38566201, 2024). "In recent years, a growing body of investigations has consistently demonstrated that SOX2 plays a pivotal role in driving distant metastasis, tumour invasion, radioresistance, and drug resistance through the induction of epithelial-mesenchymal transition (EMT) in tumour epithelial cells." (PMID 38494478, 2024).
tumor (continued). "Indeed, the key transcriptional regulator of the SCLC-A subtype, ASCL1, upregulates expression of SOX2, and this is important in both tumor establishment and MYC-dependent subtype regulation." (PMID 39456533, 2024). "This debate may be attributed to SOX2’s ability to regulate the activity of a wide range of genes that can either accelerate or prevent tumor growth." (PMID 38532463, 2024). "Of significance, SOX2 is also involved in many functions related to carcinogenesis, including promoting tumour cell proliferation, the ability to repress apoptosis, accelerating cell invasion and migration, regulating self-renewal of tumour stem cells, and metastatic potential." (PMID 39365497, 2024). "In cancer, SOX2 expression has been detected in CSC populations across various tumor types." (PMID 39463384, 2024). "Thus, SOX2 expression in MB157 cells rendered tumor cells resistant to GSI in vivo, which correlated with an increased number of invasive tumor cells (Fig. EV4G)." (PMID 39478150, 2024). "Furthermore, RNAseq data from HNO223 tumor cell lines knocked down for SOX2 or SOX9 demonstrated that 11 genes present in clinical samples were also present in clones knocked down for SOX2 or SOX9." (PMID 38275880, 2024). "Furthermore, we describe a molecular mechanism of reciprocal inhibition between Notch signaling and SOX2 that shapes tumor cell plasticity and therapeutic escape in NOTCH-driven TNBC." (PMID 39478150, 2024). "Moreover, approximately 60%–80% of tumor cells also expressed SOX2, suggesting their undifferentiated status." (PMID 36929001, 2023). "SOX2 is expressed within the tumor nests, the peri-tumor stroma and microvessels." (PMID 37859926, 2023). "Overexpression of SOX2 could rescue the attenuated tumor phenotype resulting from WAC-AS1 knockdown and miR-5047 mimic treatment." (PMID 37957698, 2023). "In the orthotopic xenograft tumor mouse models established with PDX cell lines, animals subcutaneously implanted with PDX-vector-shSOX9/SOX2/OCT4-shFTH1/FTL/TFRC or PDX-c-Jun-OE-shSOX9/SOX2/OCT4-shFTH1/FTL/TFRC cell lines exhibited comparable tumor burdens and tumor weights after GEM treatment." (PMID 37143164, 2023). "Up-regulation of CSCs genes, such as Sox2 and Oct3/4, may be observed after radiation, contributing to tumor radioresistance." (PMID 37065869, 2023). "Moreover, Sox2 and Oct4 expressionlevels correlate with the histological degree of tumor malignancy; theseproteins are often used as prognostic markers of cancer cell response totherapy and disease outcome." (PMID 37153502, 2023). "Furthermore, hypoxia upregulates CSCs genes such as Sox2 and Nanog, consequently contributing to the survival of tumor cells after radiation." (PMID 37065869, 2023). "Additionally, the plasticity of CSCs plays a significant role in promoting stemness, as evidenced by the overexpression of stemness-associated transcription factors (e.g., OCT3/4, SOX2, NANOG) among others, in diverse tumor types." (PMID 37784157, 2023). "Additionally, lower EPCAM, β-catenin, β-catenin (in the nucleus), c-Myc, and SOX2 protein levels were seen in SiHa-SNAI2-cell-derived xenografted tumor tissues compared to SiHa-Vec-cell-derived xenografted tumor tissues (p < 0.05)." (PMID 36674577, 2023). "The decrease of SOX2 or MYC in HNSCC by hDT806 was parallel to hDT806's stimulation of the tumor-intrinsic STING pathway, indicating there could be a crosstalk between these transcription factors and STING signaling that warrants further study." (PMID 37898690, 2023). "Additionally, the protein levels of SNAI2, EPCAM, β-catenin, c-Myc, and SOX2 were detected in xenografted tumor samples formed by SiHa-Vec and SiHa-SNAI2 cells." (PMID 36674577, 2023).
tumor (continued). "Tumours that have developed resistance to tamoxifen express higher levels of Sox2 and we have previously reported that Sox2, which is significantly increased in MCF-7TamR cells, alters the cytoskeleton structure from an organized to an irregular network, leading to reduced cell stiffness." (PMID 37569585, 2023). "Moreover, the protein levels of SNAI2, EPCAM, β-catenin, c-Myc, and SOX2 were also detected in EPCAMhigh-and EPCAMlow-cell-derived xenografted tumor tissues." (PMID 36674577, 2023). "They hypothesized that Sox2 inhibits tumor cell motility in cancer cells and that low Sox2 expression serves as a prognosticator to identify patients at high risk of relapse." (PMID 37888115, 2023). "The consequent high expression of SOX2 enhances many stemness hallmarks of bladder cancer cells in vitro, and increases the tumorigenic potential and, most notably, the metastatic ability of tumor cells in vivo." (PMID 36768150, 2023). "Sox2 expression is associated with maintenance of cancer stem cells or tumor-initiating cell proliferation, regulation of the epithelial-to-mesenchymal transition (EMT), and increased tumor cell migration and invasion." (PMID 38020885, 2023). "Here, we showed that tumor treatment with Vern extract or phytol resulted in the elimination of CSCs, as indicated by the decreased expression of the specific markers Nestin and Sox2." (PMID 36900417, 2023). "SOX2OT could recruit ALKBH5 and ALKBH6 to bind to SOX2 and demethylate the SOX2 transcript and subsequent SOX2 up-regulation, thereby regulating tumour cell apoptosis, cell proliferation, and TMZ resistance." (PMID 38055673, 2023). "Further, Sox2 is activated in cancer stem cells or tumor-initiating cells." (PMID 38020885, 2023). "Sox2 also inhibits double-positive cell development and tumor formation in our models." (PMID 37882674, 2023). "In addition, as a primary regulator of stemness, Sox-2 accelerates the acquisition of resistance characteristics, including tumor aggressiveness, chemoresistance, and EMT." (PMID 38201903, 2023). "Interestingly, the infiltrated macrophages were more abundant in DCX-specific and mixed region than in SOX2-specific region, indicating different tumor immune microenvironment among neuroectodermal subtypes." (PMID 36936909, 2023). "It has been recently reported that knockout of Piezo2 in SOX2+ medulloblastoma cells reduces local tissue stiffness, improves drug delivery across the blood-tumor barrier, and increases survival by altering WNT/β-catenin signaling between tumor and endothelial cells." (PMID 37762011, 2023). "Moreover, intratumoral injection of BCI-121 effectively suppressed the tumor growth/proliferation and SOX2 expression of CAL-27 cells in vivo." (PMID 37237385, 2023). "Our previous study showed that Sex-determining region Y-box2 (SOX2), a master regulator of embryonic development, drives tumor growth and invasion, promotes VM formation in CRC, however, the underlying mechanism of action remains unclear." (PMID 38044399, 2023). "In comparison to the non-tumour epithelium, we observed that the expression levels of SOX-2, NANOG and OCT4 were increased in AME parenchyma, suggesting that these molecules may be involved in the pathogenesis of AME." (PMID 36655039, 2023). "Identifying additional mechanisms that regulate the reprogramming of these enhancers could lead to new approaches to target tumor-initiating cells that depend on SOX2 overexpression." (PMID 37738673, 2023). "In hepatocellular carcinoma, radiation-induced elevated SOX2 expression in tumor cells." (PMID 37213675, 2023). "Conversely, the overexpression of Sox2 results in a greater capacity for tumor progression." (PMID 37888115, 2023). "Numerous malignancies depend on SOX2 for carcinogenesis and tumour growth, and in CCA, SOX2 over-expression was linked to poor overall survival, increased cell proliferation and invasion, and reduced cell apoptosis; however, its exact role in CCA must be clarified with more studies." (PMID 36901961, 2023).